IL6 (interleukin 6)
Diseases named in the same sentence as IL6 in open-access papers (continued):
Sharing a sentence is not in itself a finding about the gene and the disease.
Obesity (continued). "A possible hypothesis is the elevated serum levels of IL-6, C-Reactive Protein (CRP), TNF-α, and leptin in obesity may induce inflammatory response in the IVD." (PMID 37959372, 2023). "A recent systemic review highlighted improvements in inflammatory biomarkers in adults with obesity using aerobic exercise training (decreased CRP, IL-6, and TNF-α), resistance training (decreased TNF-α), and concurrent training including both aerobic and resistance training (decreased TNF-α)." (PMID 37372149, 2023). "The expression of obesity-related mediators (SphK1 and S1PR1) is enhanced in metastatic lesions of syngeneic and spontaneous breast tumor obese mice, along with elevated levels of TNF-α and IL-6." (PMID 36880535, 2023). "However, in follow-up periods longer than 3 months but less than 12 months, the impact of NSPT starts to diminish, as the IL-6 levels in GCF gradually increase in obese individuals, resulting in higher levels than those observed in non-obesity groups." (PMID 37798684, 2023). "TLR-4 activation stimulates JNK, which, in turn, promotes the production of cytokines, including interleukin (IL)-1, interleukin (IL)-6, tumor necrosis factor (TNF)-a, chemokines, and other proinflammatory compounds (Hypothalamic Inflammation and Gliosis in Obesity)." (PMID 37764744, 2023). "Interleukin-6 (IL-6) and tumor necrosis factor-alpha (TNF-α) are cytokines activated by pro-inflammatory signaling pathways in adipose tissue macrophages and are elevated in obesity." (PMID 37299403, 2023). "Adipose tissue may contribute to one-third of the total IL-6 in peripheral circulation and secrete TNF-α, and obesity is putative to resemble a low-grade pro-inflammatory state with burden of oxidative stress." (PMID 37104297, 2023). "At the same time, zinc demonstrated potential anti-inflammatory effects through cytokine signaling pathways and the reduction of plasma levels of IL-6, TNF-α, and CRP, with a protective effect against chronic low-grade inflammation, which is found in obesity and MetS." (PMID 38140353, 2023). "Therefore, the aim of our study was to assess the relationship between selected measures of obesity (BMI, WC, RFM, VAI, WHtR) and parameters of chronic inflammation (CRP, TNF-α, IL-6) in perimenopausal women." (PMID 37375693, 2023). "The Cana effect on the suppression of obesity-related inflammation in the nervous system of HFD-fed obese mice was mediated by reducing the levels of proinflammatory biomarkers and cytokines (e.g., Iba1 and IL-6) and the accumulation of macrophages." (PMID 38255143, 2023). "Nonetheless, a study conducted on children with obesity demonstrated that the increase in hepcidin is not accompanied by a significant increase in IL-6, underestimating the role of hepcidin in anemia." (PMID 38140340, 2023). "Usually, pregnant women with obesity at pre-pregnancy or becoming obese have a lipotoxic placental environment leading to increased OS and elevated concentrations of TNF-α, IL-1, IL-1β, IL-3, IL-4 and IL-6, and IFN-γ." (PMID 37891973, 2023). "Obesity can lead to insulin resistance and affect insulin secretion and utilization As obesity progresses, fatty tissue begins to secrete hormones such as tumor necrosis factor-alpha (TNF-α) and interleukin-6 (IL-6), which exacerbate insulin resistance." (PMID 37740187, 2023). "It is well known that obesity is characterized by the elevation of proinflammatory cytokines, including tumor necrosis factor-alpha (TNF-α), interleukin-6 (IL-6), and acute-phase proteins, such as C-reactive protein (CRP), leading to chronic subclinical inflammation." (PMID 37892400, 2023). "In the diet-induced obesity mice model, the purple corn cob extract treatment upregulated the M2 markers (ArgI, Fizz1, and TGFβ) and downregulated the inflammatory mediators (TNF-α, IL-6, IL-1β, and COX-2) by suppressing NF-kB signaling." (PMID 38005786, 2023).
Obesity (continued). "In fact, fat cells are known to physiologically secrete hormones (leptin, adiponectin and resistin) and pro-inflammatory cytokines including IL-6 and TNF-α, which are recognized to be elevated during obesity, and in turn stimulate the recruitment of immune cell infiltrates." (PMID 37283765, 2023). "Apart from obesity increasing insulin, IGF-1, leptin, IL-6, TNF-α and decreasing levels of adiponectin which activates the PI3K-AKT signalling pathway in CRC, high BMI inhibits methylation of PI3K-AKT signalling pathway genes, constitutively activating the pathway." (PMID 37233716, 2023). "With IL‐6 level being related to obesity, our data suggest that it is more appropriate to target BMI with weight reduction rather than IL‐6 itself, when aiming to improve exercise capacity in females." (PMID 35811337, 2022). "Interestingly, the link between Mtb infection and the immune response in adipose tissue has been evaluated and was found to affect the production of pro-inflammatory cytokines (TNF-α, IL-6, MCP-1) and leptin, which induces metabolic dysfunction in obesity." (PMID 35682832, 2022). "One such mechanism may involve the obesity-related state of chronic low-grade inflammation, as indicated by biomarkers such as c-reactive protein (CRP) and interleukin-6 (IL-6)." (PMID 35301057, 2022). "We report correlations between HOMA2-IR and scWAT fibrosis and WNT mRNA expression, as well as correlations between circulating IL-6 concentrations, macrophage infiltration and WNT mRNA expression suggesting an important role for metabolic health in addition to obesity." (PMID 35958557, 2022). "It is known that pre-pregnancy obesity and several lifestyle factors, including a diet rich in meat and processed foods, correlate directly with circulating concentrations of inflammatory biomarkers, such as CRP and IL-6." (PMID 35270396, 2022). "The condition of obesity is characterized by chronic low-grade inflammation with over-expression of inflammatory molecules and markers, such as C-reactive protein (CRP), interleukin 1 (IL-1), and interleukin-6 (IL-6)." (PMID 36615820, 2022). "Accordingly, obesity is characterized by increased levels of circulating factors including insulin, insulin-like growth factor 1 (IGF-1), leptin, and inflammatory cytokines such as IL6 and TNFα." (PMID 36010901, 2022). "In obesity conditions, adiposities release pro-inflammatory cytokines such as TNF-α and IL-6." (PMID 35204193, 2022). "ADAM17, IFITM3, IL6 and IFNE were more highly expressed in PBCs of patients with obesity." (PMID 36009555, 2022). "In OA combined with obesity, the subpatellar fat pad releases TNF-α, IL-6, IL-1, and IL-1β." (PMID 36439850, 2022). "Obesity leads to the induction of aromatase expression in adipose stromal cells (ASCs) and enhances estrogen levels as a result of increased COX-2 expression and elevated levels of proinflammatory mediators and cytokines: TNFα, IL-1, and IL-6." (PMID 36555323, 2022). "This pathway is similar to that seen in obesity, including increased production of TNF-α and IL-6." (PMID 35962192, 2022). "Obesity, combined or not with MetS, creates a higher risk of developing CKD, predisposing to a pro-inflammatory state, increased IL-6 and TNF-α and possible progression of kidney injury to terminal CKD." (PMID 35657982, 2022). "Moreover, pro-inflammatory cytokines, such as interleukin-6 (IL-6) and tumour necrosis factor-α (TNF-α), increase in states of both obesity and acute headache attacks, thus contributing to local and systematic inflammation as a prominent feature of headache." (PMID 36686472, 2022). "Moreover, obesity induced the activation of IFN, TNFα, IL-2 and IL-6 signaling in the aEC population." (PMID 36400935, 2022). "In humans, IL-6 levels increase in patients with T2DM and obesity." (PMID 36248900, 2022).
Obesity (continued). "More importantly, the LI protocol improved insulin sensitivity, reduced fasting insulinemia, improve the level of the obesity-related adiponectin, decreased the level of the pro-inflammatory marker TNF-alpha and Il-6, and positively modulated the levels of exercise-induced myokines, irisin and BDNF." (PMID 35120179, 2022). "In obesity, excessive fat accumulation results in overexpansion of adipose tissue, resulting in adipocyte cell death which promotes stimulate Inflammasomes, cytokines (TNF-α, IL-6 and iNOS) and hepatic stellate cells." (PMID 35186751, 2022). "Although WD-fed dams did not become obese, serum CRP and neutrophils increased, without a change in serum IL-6, indicative of mild, systemic inflammation in response to WD prior to attaining obesity." (PMID 36935840, 2022). "This indicates that both obesity and OSA are factors contributing to the elevation of IL-6." (PMID 36017324, 2022). "In contrast, obesity triggers the secretion of cytokines involved in osteoporosis, negative vessel remodeling, and inflammation with increased leukemia inhibitory factor (LIF), IL1β, CCL2, leptin, interferon gamma (IFNγ), IL6, and TNFα." (PMID 36010901, 2022). "In addition, secretion of pro-inflammatory cytokines (TNF-α, IL-6, and CCL2) from macrophages and adipocytes is promoted in obesity, which is considered a form of chronic inflammatory disease." (PMID 34949748, 2022). "Interestingly, obesity‐related leptin concentration significantly increased the ability of purified CD4+ T cells from lean AA patients to produce IL‐5, IL‐13, IL‐17 and IL‐6, but diminished IL‐10 release." (PMID 35734271, 2022). "Neither classic IL-6 nor trans-signalling do influence the outcome of diet-induced obesity, insulin sensitivity and glycaemic control." (PMID 36387898, 2022). "Activation of the NF-κB and MAPK pathways in obesity occurs due to exposure to immune cells to increased circulating saturated fatty acids and LPS, increasing production of pro-inflammatory cytokines, including TNF-α and IL-6." (PMID 35215414, 2022). "We found that the pro-inflammatory cytokines TNF and IL6 were higher expressed in visceral compared to subcutaneous adipose tissue of subjects living with obesity, whereas no depot-dependent difference was observed in non-obese women." (PMID 36340033, 2022). "People with obesity develop inflammation, which is characterized by an increase in the number of macrophages infiltrating adipose tissue and elevated expression and secretion of inflammatory cytokines such as TNF-α, IL-6 and IL-1β." (PMID 35745168, 2022). "Using the integrated strategy of network pharmacology and greedy algorithms, the important roles of some targets IL6, HMCGR, PPARA, and APOB for management of hyperlipidemia and obesity were highlighted in this work, which was also in accord with the previous publications." (PMID 35586687, 2022). "In the group of obese children without NAFLD (i.e., the simple obesity group), we found that inflammatory markers IL-6 and IL-32 exhibited the highest number of significant correlations." (PMID 36530698, 2022). "In obesity, white adipose tissue produces inflammatory agents, including tumour necrosis factor-alpha (TNF-α) and interleukin-6 (IL-6), which not only have local effects on the physiology of adipose tissue but additionally induce systemic effects in other organs." (PMID 36362227, 2022). "Interestingly, there is compelling evidence illustrating that polycystic ovary syndrome (PCOS) patients affected by obesity exhibit high levels of TNF-α and IL-6 in serum and adipose tissues." (PMID 35747760, 2022). "The functional framework between IL-6 and CRP may be strongly influenced by the increased production of IL-6 by human adipose tissue in cases of obesity." (PMID 34813039, 2022).
Obesity (continued). "Leptin inhibits appetite and food intake, stimulates energy expenditure, and also has pro-inflammatory effects contributing to the low-grade chronic inflammation by enhancing the TNF-α and IL-6 production and vice versa TNF-α stimulated leptin secretion from adipocytes that induces obesity." (PMID 36297569, 2022). "Interleukin-6 (IL-6) and tumor necrosis factor (TNF), two pro-inflammatory indicators, rise in response to infection, tissue injury, and states of active stress like obesity." (PMID 36330087, 2022). "Recently it was suggested that increased levels of leptin secreted by obesity altered adipose stem cells induced the EMT and CSC reprogramming of MCF7, BT20, HCC1806, and TU-BcX cancerous cells through expression of Serpine1, SNAI2, IL6, TWIST1, and PTGS2." (PMID 36077676, 2022). "Thus, along with IL-6, resistin, and TNF-α, leptin acts as an indicator of obesity initiation and insulin resistance." (PMID 36248900, 2022). "Moreover, the disorder of glucose metabolism regulation is one of the characteristics of obesity, and is often accompanied by elevated levels of chronic inflammatory markers in the liver and obese tissues, such as TNF-α, IL-6, and IL-1 β." (PMID 36232527, 2022). "Besides macrophages, the inflammatory cytokines IL6 and TNF are additionally emitted from fat tissues and are known to be increased in obesity and insulin-resistant patients." (PMID 36432581, 2022). "Unhealthy lifestyle, e.g., obesity, smoking, and alcohol consumption increase concentrations of inflammatory markers, of which especially CRP, TNF-α and IL-6 may contribute to the development of insulin resistance and cardiometabolic diseases." (PMID 35831939, 2022). "In addition, obesity has been recognized as proinflammatory state leading to elevated level of proinflammatory cytokines, such as TNF and interleukin (IL)-6, which favor the development of cancer." (PMID 35120118, 2022). "The level of interleukin 6, according to available research, increases both in MIS-C and obesity." (PMID 36225207, 2022). "Mice lacking IL-6 display obesity, hepatosteatosis, liver inflammation and insulin resistance compared to wildtype mice on a standard chow diet, with increased glucose intolerance and insulin resistance in mice fed with a high fat diet compared to controls." (PMID 35684160, 2022). "In addition to influencing stem cell differentiation, the proinflammatory state that occurs in obesity increases the levels of cytokines that stimulate osteoclast formation and activity by affecting the RANKL/RANK/OPG pathway, such as TNF-α and IL-6." (PMID 35955431, 2022). "Red ginseng-derived saponin fraction, 6-gingerol (found in ginger), and lunasin (identified in several grains) inhibit obesity-induced inflammatory responses by inhibiting the production of inflammatory mediators MCP-1 and IL-6 in co-culture conditions with 3T3-L1 and RAW264.7 cells." (PMID 35807667, 2022). "IL‐6 is a key player in COVID‐19 pathogenesis and is often elevated in infected patients with obesity as compared to those without obesity." (PMID 35837843, 2022). "Obesity results in the increased secretion not only of TNF but also of resistin, IL1β and IL6." (PMID 36233290, 2022). "Research from our group showed that in obese Zucker rats, peritoneal macrophages present a local dysregulation in the constitutive or spontaneous release of pro-inflammatory cytokines such as IL-1β, INF-γ, IL-6, and TNF-α, contributing to the low-grade systemic pro-inflammatory state in obesity." (PMID 35276970, 2022). "Unlike TNF-α and IL-6, adiponectin’s serum concentrations decrease with obesity, and recent studies have shown that a high serum adiponectin also signifies a renal dysfunction." (PMID 35054932, 2022).
Obesity (continued). "The correlations between gut microbiota (based on OTUs) and obesity related indexes (including body weight gain, percent of epididymal fat weight, the levels of TG, TC, HDL, LDL, TNF-α, IL-6, IL-10, and IL-4) were investigated using the Pearson correlation analysis." (PMID 35807812, 2022). "Using the fixed-effect model, the combined effect amount SMD = −0.28, 95% CI = −0.62~0.06 (p = 0.10), indicating that training can reduce the level of IL-6 in adolescents with obesity, but the result was not significant." (PMID 36293806, 2022). "Inhibition of IL-6 did not further delay progression in lean animals, thereby suggesting that obesity promotes resistance to anti-VEGF therapy in breast cancer specifically by IL-6." (PMID 35186923, 2022). "Luminex analysis showed that in the HFD-induced obesity mouse model, there was an obvious increase in serum proinflammation cytokines such as TNF-α, MCP-1, IL-12, IL-1β, IL-6, CCL3, CXCL16, and Resistin, which were further alleviated significantly in the CD226KO group." (PMID 34823548, 2021). "Obesity leads to a proinflammatory milieu characterized by increased levels of TNF-α, plasminogen activation inhibitor-1, angio-tensinogen, plasminogen activation inhibitor-1, IL-6, leptin, and decreased adiponectin levels which enhance endothelial functions." (PMID 34249177, 2021). "Furthermore, quercetin supplementation significantly suppressed the proinflammatory cytokines TNFα, IL-6, and MCP-1 levels in eWAT and sera, suggesting its ability to reduce obesity-induced adipose tissue and systemic inflammation." (PMID 33805912, 2021). "One recent study suggested a negative correlation between βS and IL-6 levels in an animal model of obesity-related chronic inflammation." (PMID 33997001, 2021). "This cross-sectional study of adolescents with obesity without overt MetS showed higher hepcidin and IL-6 levels than those of their lean counterparts." (PMID 34065056, 2021). "Obesity, regardless of model, is marked by increased levels of a wide array of proinflammatory cytokines, like IL-6, TNF-α, and IL-1β, in the expanding tissues and circulation." (PMID 33554957, 2021). "Thus, pharmacologic or other approaches that could modulate macrophage activity and IL-4/IL-6 production in the adipose tissue during aging could be exploited therapeutically in the recovery of beige fat to potentially improve metabolic health, as been done in the field of obesity." (PMID 34423787, 2021). "Moreover, IL-6 and TNF-α, which are elevated during obesity, have been shown to promote osteoclast differentiation, thereby prompting bone loss." (PMID 33554957, 2021). "Most of ceramides, dhCers, and SMs showed unfavorable correlations with obesity (rs = 0.06 to 0.15), triglycerides/HDL-cholesterol (rs = 0.06 to 0.28), CRP (rs = 0.06 to 0.17), IL-6 (rs = 0.07 to 0.13), adiponectin (rs = −0.06 to −0.14), and RBP4 (rs = 0.06 to 0.24)." (PMID 34208976, 2021). "All current in-silico findings might display the binding capability of metformin with IL-6, CCL2 proteins in obesity, and hypertension." (PMID 34334083, 2021). "IL-6 and TNF-α were associated with a slightly higher grade of inflammation in children with obesity than the normal-weighted controls; however, this was not statistically significant." (PMID 33883996, 2021). "According to several studies, in obesity and physical inactivity, dysfunctional adipocytes start secreting higher amounts of the pro-inflammatory cytokines IL-1 (α and β subtypes), TNF-α, and IL-6." (PMID 34436472, 2021). "Inspired by the previous studies, we speculated that miR-194 might be involved in the regulatory effect of IL-6 and PA on GLP-1 synthesis during obesity." (PMID 33479193, 2021). "Indeed, circulating levels of several inflammatory cytokines (i.e., CRP, IL‐1β, IL‐6, IL‐8, MCP‐1, and TNFα) have been shown to be increased in obesity." (PMID 34110720, 2021).